IGF1 (insulin like growth factor 1)
Diseases named in the same sentence as IGF1 in open-access papers (continued):
Sharing a sentence is not in itself a finding about the gene and the disease.
Insulin resistance (continued). "This suggests that hyperinsulinemia may be a mechanism that leads to the observed tissue IGF1 resistance in human obesity and type 2 diabetes, in addition to the more characterized insulin resistance." (PMID 40105689, 2025). "Insulin resistance can result in elevated insulin and insulin-like growth factor-1 levels, which excessively stimulate androgen secretion, disrupt normal follicular development and ovulation, and may ultimately lead to infertility." (PMID 39815248, 2025). "In BRCA gene mutation carriers, defective ER signaling promotes insulin resistance; however, compensatory high levels of insulin and IGF-1 do not successfully improve glucose uptake." (PMID 41514592, 2025). "Several mechanisms have been proposed whereby the increased risk among patients with T2D is associated with the metabolic disorders characteristic of this disease (e.g., hyperglycemia, insulin resistance, hyperinsulinemia or elevated levels of insulin-like growth factor 1—IGF-1)." (PMID 41008833, 2025). "Several mechanisms that could result in GC genesis together are obesity, insulin resistance, IGF-1, angiogenesis, adipokines, and higher estrogen values." (PMID 40572713, 2025). "Additionally, obesity-induced insulin resistance disrupts insulin/IGF-1 signaling, thereby overactivating the PI3K/Akt/mTOR pathway." (PMID 41048699, 2025). "Specifically, the excess estrogen, insulin resistance, and elevated IGF-1 levels commonly observed in obesity may promote tumor growth and angiogenesis." (PMID 40722754, 2025). "Additionally, reductions in hormones such as IGF-1, testosterone, and myokines exacerbate insulin resistance." (PMID 41003141, 2025). "Additionally, VAT accumulation is capable of inducing insulin resistance, subsequently leading to reduced levels of growth hormone and insulin-like growth factor-1 (IGF-1) two essential hormones for maintaining bone homeostasis and regulating lipid metabolism." (PMID 41220706, 2025). "IGF-1 is essential for optimal sensitivity to insulin, and deficient IGF-1 levels may lead to insulin resistance." (PMID 40141202, 2025). "In addition, insulin resistance can further inhibit muscle growth by affecting the function of the growth hormone-insulin-like growth factor-1 (GH-IGF-1) axis." (PMID 40873790, 2025). "Asynchronous termination of these drivers after birth would lead to a biphasic postnatal dysregulation of IGF-1 tone in the infant, with the early insulin resistance-driven overgrowth in the first life year coinciding with the well-documented and specific accelerated development and growth in ASD." (PMID 40429628, 2025). "Additionally, resistin contributes to insulin resistance, which not only reduces muscle glucose uptake but also disrupts anabolic signaling pathways like IGF-1/Akt/mTOR, essential for muscle protein synthesis." (PMID 39983655, 2025). "Additionally, intermittent fasting and caloric restriction strategies demonstrated efficacy in lowering insulin resistance, reducing IGF-1 signaling, and enhancing the effectiveness of cancer therapies." (PMID 40282189, 2025). "In addition, insulin resistance and dysregulation of the growth hormone (GH)/insulin-like growth factor I (IGF-1) axis suppress muscle synthesis." (PMID 41487675, 2025). "One key pathway is insulin resistance and hyperinsulinemia: adiposity, especially visceral fat, drives chronic insulin resistance, leading to elevated circulating insulin and IGF-1 levels, which have mitogenic and anti-apoptotic effects on colonic epithelial cells." (PMID 41041441, 2025). "Insulin resistance, a key feature of metabolic syndrome, results in compensatory hyperinsulinemia, increased IGF-1 secretion, and reduced levels of sex hormone-binding globulin (SHBG), thereby increasing free androgen bioavailability and amplifying inflammatory pathways." (PMID 40868844, 2025). "Insulin resistance promotes cancer proliferation through increased bioavailability of IGF‐1." (PMID 40387523, 2025).
Insulin resistance (continued). "In contrast, improvements in insulin resistance and liver health could improve the liver's responsiveness to GH, promoting IGF-1 secretion." (PMID 40520449, 2025). "Insulin resistance is a primary pathological mechanism causing both MASLD and sarcopenia, initiating from skeletal muscle loss and leading to increased lipolysis and dysregulation of the GH/IGF-1 axis." (PMID 40852370, 2025). "Thus, hyperglycemia, insulin resistance, and inflammation synergistically suppress IGF-1 in uncontrolled T2DM." (PMID 41393761, 2025). "These promote chronic low‐grade inflammation, insulin resistance, and hyperinsulinemia, which enhance colonic epithelial proliferation and adenoma formation via pathways like IGF‐1 signaling and adipokine dysregulation (e.g., elevated leptin and reduced adiponectin)." (PMID 41332918, 2025). "A recent population-based cohort study demonstrated that PPI use was associated with increased insulin resistance as measured by HOMA-IR levels; possible mechanisms include PPI-induced hypomagnesemia and suppression of insulin-like growth factor-1(IGF-1) due to PPIs." (PMID 40459644, 2025). "Furthermore, our results indicated that anorexigenic IGF1 signaling occurs within the hypothalamus and that hyperinsulinemia-induced insulin resistance coincided with IGF1 resistance, potentially revealing a new mechanism contributing to obesity." (PMID 40105689, 2025). "Insulin resistance and hyperinsulinemia, features of type 2 diabetes, increase the bioavailability of estrogen and insulin-like growth factor (IGF)-1, which promote endometrial proliferation and are conducive to the development of endometrial cancer (especially type I)." (PMID 40877024, 2025). "It has been speculated that IGF-1 acts positively on patients with insulin resistance, as it exerts insulin-like activity in regulating glucose uptake by tissues, and it has been shown that treatment with recombinant IGF-1 can increase sensitivity to glucose." (PMID 41153350, 2025). "Additionally, insulin resistance improves after transsphenoidal surgery, correlating with serum IGF-1 levels before and after surgery." (PMID 40088375, 2025). "However, in vivo studies have shown that insulin resistance leads to elevated levels of circulating insulin, which increases the bioavailability of IGF-1, further promoting cellular proliferation and survival." (PMID 41440200, 2025). "The proposed pathophysiological links between MetS and carcinogenesis include chronic systemic inflammation, increased oxidative stress, insulin resistance, hyperinsulinemia, and the dysregulation of growth-promoting pathways such as the insulin-like growth factor-1 (IGF-1) axis." (PMID 40572713, 2025). "Notably, the study revealed the costimulatory effects of TNF-α and IGF-1 on preeclampsia with increased insulin resistance." (PMID 41155321, 2025). "In addition to insulin resistance, patients with CKD often experience hyperparathyroidism, vitamin D deficiency, and low levels of growth hormone (GH) and insulin-like growth factor 1 (IGF-1)." (PMID 41262737, 2025). "Regarding laboratory findings, IGF-1 values are preferred as the gold standard for diagnosis given that its values are not affected by glucose intake and its levels correlate with soft tissue enlargement and insulin resistance." (PMID 40941625, 2025). "Hypothesized mechanisms linking metabolic syndrome to GC include insulin resistance-related increased insulin-like growth factor-1 availability and obesity-derived chronic inflammation." (PMID 40245012, 2025). "So, hyperinsulinemia or insulin resistance may lead to an increased production of IGF-1, which, in turn, contributes to cancer promotion by stimulating cell proliferation." (PMID 41374092, 2025).
Insulin resistance (continued). "This case-control study demonstrates that lower circulating IGF-1 levels are strongly associated with poor glycemic control in geriatric patients with T2DM, and are linked to greater insulin resistance, longer disease duration, inflammation (elevated TNF-α), and adverse lipid profiles." (PMID 41393761, 2025). "The transition period is marked by a reduction in insulin levels and tissue responsiveness of this hormone, with an increase in growth hormone (GH) levels and a reduction in IGF-1, characterizing uncoupling of the somatotropic axis and peripheral insulin resistance." (PMID 41472162, 2025). "The data also revealed that patients with a normal Homeostatic Model Assessment for Insulin Resistance (HOMA-IR) exhibited a significantly higher mean IGF-1 compared to those with a high HOMA-IR (> 2.5), with values of 192.83 versus 143.85, respectively (P = 0.001)." (PMID 39578883, 2024). "Additionally, it has been discovered that silencing Klotho in high glucose-treated cells increased IGF1R, p-IGF1R and IGF1 expression, and activates the IGF1/PI3K/Akt/mTOR signalling pathway, known to be associated with insulin resistance." (PMID 38486352, 2024). "Whether HFSD-induced hyperlipidemia, increased IGF-1, or insulin resistance itself was responsible for the greater neointimal growth in HFSD-fed mice compared to LFD-fed mice in the present study remains unclear." (PMID 39195275, 2024). "Insulin resistance leads to elevated insulin and insulin-like growth factor 1 (IGF-1), which is an effective growth stimulator and may induce scleral tissue growth and elongation of the eye axis, thus leading to the development of myopia." (PMID 38191303, 2024). "Hyperglycemia, insulin resistance, elevated insulin, and insulin-like growth factor-1 (IGF-1) levels, inflammatory cytokines, dyslipidemia, increased leptin, and decreased adiponectin have all been attributed to the increased risk of cancer in patients with diabetes." (PMID 39020360, 2024). "Interestingly, we found that AC supplementation during early life attenuated insulin resistance and suppressed Igf1 expression later in life exclusively in female mice." (PMID 39125288, 2024). "It has been hypothesized that lower levels of IGF1 may predict the development of diabetes, insulin resistance, metabolic syndrome, and cardiovascular disease." (PMID 39409124, 2024). "IGF-1 has been proposed as an indirect marker of hepatic insulin resistance." (PMID 39594641, 2024). "Additional effects on increase in IGF1 with weight loss, more prominent after LAGB procedure, and reduction in TSH in bariatric patients have likely contributed to improved insulin resistance, metabolic rate and improved body composition parameters in patients undergoing weight loss interventions." (PMID 39014246, 2024). "It has been shown that insulin resistance (IR) and activation of the insulin receptor, as well as the insulin-like growth factor 1 (IGF-1) signaling pathways, play pivotal roles in both the initiation and progression of hepatocarcinogenesis in patients with DM." (PMID 38434702, 2024). "The inhibition of myostatin increases IGF1 signaling and reduces insulin resistance." (PMID 38791164, 2024). "Additionally, it appears that insulin resistance is accompanied by IGF-1 resistance and is connected with a malfunction in the activity of IRS-152." (PMID 38987609, 2024). "In this regard, the literature also mentions insulin resistance and hyperinsulinemia, as well as insulin-like growth factor-1 (IGF-1), hyperglycemia, and toxic elements being released, even including advanced glycation end products (AGEs) and reactive oxygen species (ROS)." (PMID 38785834, 2024). "In addition, high amount of fiber and phytochemicals in this pattern can play a key role in prevention of cancer by reducing circulating estrogens and androgens, inflammation, insulin resistance, and IGF-1 concentration." (PMID 38500219, 2024).
Insulin resistance (continued). "Physiological mechanisms such as age-related hormonal levels (growth hormone, insulin-like growth factor 1, sex hormones, etc.), insulin resistance, inflammation, and oxidative stress levels contribute to these more pronounced differences in females and old elderly subgroups." (PMID 38966224, 2024). "Insulin resistance may affect bone health by impairing the insulin-like growth factor-1 (IGF-1) signaling pathway." (PMID 39720256, 2024). "Moreover, chronic inflammation induces insulin resistance and reduces levels of anabolic hormones, mainly insulin-like growth factor 1 (IGF-1), which further exacerbates muscle protein breakdown." (PMID 39433511, 2024). "Moreover, a previous study demonstrated that IGF-1 can promote adipogenesis, resulting in increased lipid storage and decreased insulin resistance." (PMID 38988981, 2024). "Additionally, insulin resistance is often accompanied by hyperinsulinemia, which leads to increased levels of free insulin-like growth factor-1 (IGF-1), a known promoter of endometrial cell growth." (PMID 39850480, 2024). "Hypoprolactinemia is associated with agalactia, low levels of IGF-1, elevated levels of triglycerides and low HDL cholesterol levels, obesity, and insulin resistance, all of which are associated with metabolic syndrome, type 2 diabetes mellitus, NAFLD, and sexual dysfunction." (PMID 39425884, 2024). "The increased levels of free serum IGF-1 due to insulin resistance in these patients may promote hepatocarcinogenesis via autophagy, leading to a poor prognosis in HCC patients with type II DM." (PMID 38254739, 2024). "Influencing mechanisms may involve insulin, IGF-1, insulin resistance, endogenous hormones, leptin, adiponectin, inflammatory factors and other factors." (PMID 39011481, 2024). "In addition, insulin resistance also promotes the activity of insulin-like growth factor-1, an important factor for cell growth, proliferation, and survival." (PMID 39125385, 2024). "Additionally, studies have indicated that brain insulin resistance and insulin-like growth factor 1 (IGF-1) resistance both play a large role in the development of AD, earning it the name type 3 diabetes." (PMID 38255204, 2024). "In patients with type 2 diabetes, several variables could affect IGF-1 levels such as insulin resistance, BMI, glycaemic control, inflammatory cytokines, IGFBPs." (PMID 39578883, 2024). "Insulin resistance is influenced by various factors including BMI and body fat distribution, and primarily driven by the growth hormone/insulin-like growth factor-1 (GH/IGF-1) axis during adolescence." (PMID 40302954, 2024). "Furthermore, increased levels of PA have been shown to improve insulin resistance and interact with the levels of various circulating tumor-promoting proteins, such as insulin-like growth factor-1 (IGF-1), which has both mitogenic and anti-apoptotic effects." (PMID 38339381, 2024). "Genetic causal modelling indicates negative effects of insulin resistance on childhood and adult adiposity, and negative effects of IGF-1 resistance on childhood adiposity." (PMID 39174749, 2024). "Additionally, insulin resistance triggers the release of insulin-like growth factor 1 and insulin receptor substrate 1, influencing cell proliferation and apoptosis, contributing to hepatocarcinogenesis." (PMID 38987736, 2024). "IGF-1 also reduced insulin resistance in our model confirming the results of previous studies." (PMID 39759002, 2024). "Therefore, the increased IGF-1 expression in Arctic foxes also likely promotes lipid accumulation in adipose tissue and prevents insulin resistance." (PMID 38988981, 2024). "Participants in the High ATIR group had the highest prevalence of IGT (25%), and significantly higher body fat percentage, whole-body insulin resistance, and levels of insulin-like growth factor-1 and dehydroepiandrosterone sulfate (DHEA-S) than the other two groups." (PMID 39377071, 2024).
Insulin resistance (continued). "The anticancer effect of metformin can also inhibit tumor growth through dietary control, such as reducing blood glucose and insulin resistance and further reducing the levels of insulin and insulin-like growth factor-1 (IGF-1), thus inhibiting the growth of cancer cells." (PMID 38286894, 2024). "Insulin resistance induced by MetS might promote carcinogenesis through insulin, insulin-like growth factor 1 signaling, and systemic inflammation." (PMID 37324025, 2023). "Furthermore, an increase in growth hormone (GH) and a decrease in insulin (Ins) attended by insulin resistance (InsR) and reduced IGF-1 concentrations occur, which together are highly likely to determine the observed metabolic adaptation." (PMID 37835703, 2023). "This aspect might be relevant for better defining the complicated relationship between MetS, insulin resistance, and IGF-1." (PMID 37106164, 2023). "One of the biological mechanisms involved mentions insulin resistance and IGF-1." (PMID 37374352, 2023). "Similar to the high insulin concentration that results from insulin resistance, IGF-1 levels may initially increase to compensate for IGF-1 resistance before gradually becoming depleted." (PMID 36670169, 2023). "The microRNA miR-122 plays a role in the onset of insulin resistance through the inhibition of insulin-like growth factor 1 expression, which may relate to the role of insulin resistance in PCOS." (PMID 37367913, 2023). "For instance, insulin resistance and hyperinsulinemia secondary to obesity is associated with decreased levels of hepatic IGF Binding Proteins (IGF-BP) and elevated levels of unbound insulin-like growth factor-1 (IGF-1)." (PMID 37233716, 2023). "Hyperglycemia results in insulin resistance and upregulation of IGF‐1." (PMID 35719035, 2023). "The deterioration of IGF-1 synthesis aggravates the state of insulin resistance." (PMID 37373743, 2023). "Additionally, ablation of IGF1 signaling in macrophages has been shown to disrupt endocrine IGF1-mediated signaling, resulting in a significant increase in insulin resistance in mice." (PMID 37564976, 2023). "As in muscle, hybrid IR/IGF-1R receptors are formed, and their abundance is increased in “wild-type” T2DM; of note, it is proposed that hybrid receptors could contribute to insulin resistance by binding IGF-1 with higher affinity than insulin." (PMID 36882643, 2023). "Other theories of the relationship between breast cancer and BMI include insulin resistance in this population and insulin-like growth factor-1 (IGF-1) upregulation leading to cell proliferation and increased free estrogen levels through a reduction in sex-hormone-binding globulin." (PMID 37626871, 2023). "Therefore, we consider that in GHPA patients, high levels of GH/IGF-1 lead to elevated circulating UA levels through the induction of insulin resistance." (PMID 37818085, 2023). "Similarly, the genetic polymorphisms in different genes such as CAMK2, IGF1, IRS1, GCKR, PPARG, GCK1, and KCTD1 are found associated with insulin resistance and T2DM." (PMID 37829557, 2023). "Protective effects of the drugs may be through correlations between SIRT-1/adipokines/IGF-1 and PPARγ, improving the cross-talk between insulin resistance, obesity markers, liver dysfunction, and TNF-α." (PMID 36991247, 2023). "In fact, insulin resistance (IR) together with insulin-like growth factor 1 (IGF1) resistance (IGF1R) have been reported to be installed in neurons from human postmortem hippocampi of AD subjects, involving defects in the signaling cascades following insulin receptor activation." (PMID 38003671, 2023). "Metabolically, the aging process involves extensive alterations in body composition and insulin resistance, as well as promotes physiological declines in multiple signaling pathways including growth hormone, insulin/insulin-like growth factor 1 (IGF-1), and sex steroids regulation." (PMID 36557788, 2022).